MMP2 (matrix metallopeptidase 2)
Diseases named in the same sentence as MMP2 in open-access papers (continued):
Sharing a sentence is not in itself a finding about the gene and the disease.
melanoma (continued). "So far, published data has demonstrated that the tissue over-expression of VEGF, MMP-2, MMP-9, and TIMP-1 has an adverse effect on the course of the disease and survival of melanoma patients." (PMID 26002577, 2015). "Mechanistically, we show that SPRY4 is negatively regulated by MT1-MMP via an MMP2/RAC1 pathway, and importantly, negatively modulates MT1-MMP dependent cell migration in melanoma cells." (PMID 26392417, 2015). "The aim of presented study was to evaluate the clinical utility of serum concentrations of VEGF, MMP-2, MMP-9, TIMP-1, and YKL-40 in patients with melanoma at locoregional stage." (PMID 26002577, 2015). "Monoclonal antibodies against MMP-2 and MMP-9 were also included in this experiment because both have a role in melanoma development." (PMID 24788523, 2014). "The Ln-5γ2 chain, MMP-2, and MT1-MMP act cooperatively and required for highly aggressive melanoma tumor cells to engage in VM when cultured on a 3-D ECM." (PMID 24628713, 2014). "Ectopic expression of these miRNAs in melanoma cells differentially alters the expression of five exemplar TargetScan-predicted target genes: ADAR1, ITGB8, TGFBR2, MMP2 and VEGF-A." (PMID 24920276, 2014). "Artemisinin down-regulates MMP-2 levels in human melanoma cells and MMP-1, MMP-2 and MMP-9 levels in mouse embryonic stem-cells derived from embryoid bodies." (PMID 24467887, 2014). "The differential effect of miR-17-5p and miR-20a on gene expression in melanoma cells was further studied by focusing on four TargetScan-predicted target genes: ITGB8, TGFR2, MMP2 and VEGF-A." (PMID 24920276, 2014). "Recent studies have indicated that MMP-2 and MT1-MMP expression was significantly related to VM formation in melanoma and ovarian carcinoma cells in 3-D culture." (PMID 24628713, 2014). "A recent report on B16F10 melanoma cells showed that CSE1L overexpression triggered microvesicle generation, whereas CSE1L knockdown diminished Ras-induced microvesicle generation, MMP-2/MMP-9 secretion, and metastasis." (PMID 23369209, 2013). "This review has focused on five molecules involved in melanoma metastasis – MCAM, Gal-3, CSPG4, MMP-2, and PAX-3." (PMID 24069584, 2013). "The chondroitin sulfate chains of CSPG4 have been shown to bind both pro-MMP-2 and MT3-MMP, an MT-MMP that is expressed on vertical growth phase melanoma and is important for melanoma invasion into collagen gels." (PMID 24069584, 2013). "For example, treatment with the MSA paclitaxel impaired secretion of MMP-2 and MMP-9 and significantly reduced the invasion of melanoma cells." (PMID 23631818, 2013). "Stat3 activation was found to play an important role in angiogenesis, invasion and brain metastasis formation of melanoma cells through dysregulated expression of bFGF, VEGF and MMP-2." (PMID 23344048, 2013). "Nuclear Gal-3 contributes to melanoma metastasis by regulating multiple genes such as VE-cadherin, MMP-1, MMP-2, interleukin 8 (IL-8), and autotaxin." (PMID 24069584, 2013). "IL-1β induces expression of MMP-2 and -9 to degrade the ECM, allowing transendothelial migration, while TNF-α increases melanoma cell migration by upregulating MMP-2 and -9 expression." (PMID 24223987, 2013). "SOCS1 overexpression led to activation of STAT3 signaling and increase of MMP-2, and SOCS1−high melanoma cells enhanced invasive properties." (PMID 23231923, 2012). "Matrix metalloproteinases, especially MMP-2, MMP-9 and MT1-MMP (also named MMP-14), are largely involved in extracellular matrix degradation and melanoma cell migration." (PMID 22539938, 2012). "The reduction in invasiveness we observe appears at odds with the finding that amino-truncated ALCAM expression served to disrupt ALCAM junctions and to reduce MMP-2 activation, but actually increased the invasive capacity of BLM cutaneous melanoma cells." (PMID 22745734, 2012).
melanoma (continued). "Using lentiviral vectors, expression of PEX was shown to block bFGF induced MMP-2 activation, cell migration, proliferation, tube formation and CAM angiogenesis besides inhibiting human melanoma (M21L) tumor growth in nude mice." (PMID 22267953, 2011). "In melanomas, higher levels of MMP-1, MMP-2, MMP-9, and MMP-14 have been observed in the more invasive and metastatic tumors." (PMID 20843370, 2010). "In turn, integrins overexpression stimulates MMP-2 and MMP-7 in melanoma cells, increasing their invasive potential." (PMID 20631829, 2010). "Consistent with these in vitro results, the expression of transcripts coding MMP-2, MMP-9, and TNF-α is similarly inhibited in the melanoma tumors recovered from HB-19 treated RET mice." (PMID 20573279, 2010). "Endothelin B-receptor (ETB-R) is overexpressed in human melanoma, activation of the ETB-R pathway increases the expression of MMP-2 and MMP-9 and ETB-R antagonist induced an inhibition of tumor growth and a decrease of vascular density." (PMID 24281035, 2010). "Thalidomide promoted B16F10 melanoma cell necrosis and inhibited VEGF, NF-κB, PCNA, MMP-2 and MMP-9 expression." (PMID 18983651, 2008). "The results of MMP-2 secretion assays also showed that increased CAS expression enhanced MMP-2 secretion, and reduced CAS expression decreased MMP-2 secretion of B16-F10 melanoma cells." (PMID 18597698, 2008). "We have reported previously that OPN expression in human melanoma cells increases CD44 surface expression, MMP-2 secretion, and cell migration." (PMID 17343740, 2007). "Thereafter, increased mRNA levels of MMPs were reported in TCDD-treated human cells, such as, MMP1 in keratinocytes and melanoma cells, MMP2 in melanoma cells, MMP3 and MMP7 in endometrial cells, and MMP9 in prostate cancer cells and melanoma cells." (PMID 16704738, 2006). "Immunofluorescence and western blot analysis confirmed reduced MMP‐2 and MMP‐9 protein expression and an increased Bax/Bcl‐2 ratio following emodin treatment, which indicates emodin's potential as a therapeutic option for highly metastatic melanoma." (PMID 41546170, 2026). "Furthermore, dioscin decreased the secretion of MMP‐2, MMP‐9 and VEGF from melanoma cells treated with dioscin." (PMID 41546170, 2026). "Vimentin is a key EMT biomarker present in mesenchymal cells and usually overexpressed during cancer metastasis, while MMP-2 and MMP-9 are peptidases involved in extracellular matrix remodeling and tumor invasive processes, favoring melanoma spreading and metastasis." (PMID 39981176, 2025). "Additionally, Wnt5a overexpression in melanoma cells activates PKC, upregulating MMP-2 and promoting cell spread." (PMID 40399946, 2025). "By suppressing MMP-2 and MMP-9 activity in HCT116 cells (human colorectal adenocarcinoma), SK-MEL-5 cells (malignant melanoma), and MDA-MB-231 cells (breast adenocarcinoma), laminaran sulphate, which is extracted from the brown alga Fucus evanescens, was shown to be an effective anti-migratory drug." (PMID 41321380, 2025). "A high level of MMP-2 and MMP-9 has been found in several cancer types, such as those of the bladder, breast, bronchopulmonary, cervical, colon, glioma, larynx, lung, ovary, melanoma, myeloma, esophagus, pancreas, prostate, skin, and stomach." (PMID 38672151, 2024). "Nevertheless, melanoma and glioblastoma share only two overlapping targets (EGFR and MMP2)." (PMID 39628999, 2024). "Regarding modulations of MMPs and angiogenesis as the important molecular targets for the anti-metastatic action of apigenin, MMP2 in melanoma cells and MMP9 in melanoma and ovarian cancer cells, and vascular cell adhesion protein 1 (VCAM-1) in B16-BL6 melanoma cell were regulated." (PMID 38515580, 2024). "Others described melanoma cell sEVs containing various signaling molecules from the MAPK family, HSP70, Tyrp2, and several microRNAs or pro-angiogenic factors (IL-8, VEGF, MMP-2, EGFR) that regulate the proliferation, migration, and invasion capabilities of neighboring cells." (PMID 39596498, 2024).
melanoma (continued). "MMP-2 and MMP-9 are involved in angiogenesis and melanoma cell invasiveness." (PMID 38794128, 2024). "Both MMP-2 and MMP-9 are considered essential for the advancement of melanoma cells." (PMID 39582871, 2024). "MMP2 and MMP9 could be released in proximity of the contact regions also by the small exoplasmic vesicles observed on protrusions of melanoma cells." (PMID 37371639, 2023). "Melanoma cells were demonstrated to release exosomes containing factors regulating angiogenesis, such as the vascular endothelial growth factor (VEGF), IL-6, and matrix metalloproteinase 2 (MMP2), due to WNT5A signaling." (PMID 36766698, 2023). "Based on several published clinical data summarized in TISIDB, there was a significant difference in MMP2 expression between melanoma immunotherapy response and no-response." (PMID 36788565, 2023). "Notably, when comparing SK-Mel-28 and FO-1 melanoma cells to A375 cells, which are reported to exhibit higher metastatic potential, enhanced expression levels of AXL, uPAR, and MMP2 were observed in A375 cells." (PMID 37507910, 2023). "Finally, the expression levels of SNAI2, MMP2, MIF, and AP1S2 were elevated in melanoma cells of MM, consistent with the results of previous studies." (PMID 37880239, 2023). "According to a study, HDM plays a role in allowing MMP-2 to interact with integrin αVβ3, a protein, in melanoma cells and endothelial cells, even without the presence of the Arg-Gly-Asp (RGD) motif that is typically involved in such interactions." (PMID 37513440, 2023). "It has been reported that SB-3CT, an MMP2/9 inhibitor, could improve the efficacy of anti-PD-1 and anti-CTLA-4 treatment in mouse models with melanoma and lung cancer via regulating PD-L1 expression." (PMID 36823234, 2023). "Through leveraging gene signatures in predicting the durability of drug response, this study also identified the expression levels of the genes MMP2, SPARC, and HMOX1 as having a good predictive value in predicting the emergence of chemoresistance to BRAF/MEK inhibitor therapy in melanomas." (PMID 37176114, 2023). "Furthermore, these authors observed that the immunohistochemical heterogeneity of LAM cells was associated with different patterns; for example, larger LAM cells stained more strongly for MMP-2, MMP-9, and Human Melanoma Black-45 monoclonal antibody." (PMID 36817769, 2023). "Highly aggressive melanoma cells displayed more prominent effects on the CAFs phenotype in terms of enhanced motility, expressed as an elevated migration and invasion ratio, as well as higher area of digestion in MMP2 and MMP14 proteolytic activity compared to less aggressive melanoma cells." (PMID 36831295, 2023). "Another study showed that melanoma-derived exosomes contain VEGF, IL-6, and MMP2." (PMID 35740619, 2022). "Laminaran sulfate isolated from the brown alga Fucus evanescens was shown to be a potent anti-migratory agent by inhibiting MMP-2 and MMP-9 activity in human colorectal adenocarcinoma (HCT116 cells), malignant melanoma (SK-MEL-5 cells), and breast adenocarcinoma (MDA-MB-231 cells)." (PMID 35621924, 2022). "Next, we evaluated whether Bcl2L10was able to affect the activity of matrix metalloproteinases MMP2 and MMP9,which we previously demonstrated to be modulated by Bcl-2 and Bcl-xL in melanoma." (PMID 36046354, 2022). "In melanoma, metformin has been found to inhibit cancer cell invasion, proliferation, and epithelial–mesenchymal transition through the activation of AMPK and the inhibition of MMP2 and MMP9 expression." (PMID 36139556, 2022). "For example, BBR inhibits MMP-2 and MMP-9 expression by downregulating TGF- β1 and the COX-2/PGE2–JAK2/STAT3 axis in breast cancer, and epithelial-mesenchymal transition in melanoma by inhibition of the RARα/β-mediated PI3K/AKT signaling pathway." (PMID 36678712, 2022). "Hence, MMP2 and MMP9 were chosen as tumorigenic indicators to exhibit the correlation between PCDH9 and melanoma suppression." (PMID 36452505, 2022).
melanoma (continued). "However, in the present study, we indicated that TLR4 was a ligand of PA, which promoted the lung metastasis of melanomas by activating TLR4 as well as the nuclear translocation of pNF-κB, influencing the translation of E-cadherin, MMP2, and Vimentin." (PMID 36422271, 2022). "MMP2 has been believed to act as a pro-tumorigenic and pro-metastatic factor in different cancers aside from melanoma, whereas higher MMP9 levels have been found in patients with melanoma than in healthy population, making it a promising marker for melanoma." (PMID 36387162, 2022). "Also, in melanoma, PI3K activation triggered by VEGF-A/VEGF-R1 binding contributes to VM by stimulating MMP-14-mediated MMP-2 activation and subsequent tumour cell migration and tube formation." (PMID 36224457, 2022). "Interestingly, co-treatment of an MMP-2/-9 inhibitor and PD-1 or CTLA-4 blockade enhanced the therapeutic efficacy in the treatment of mouse models of melanoma and lung cancer." (PMID 35558554, 2022). "Therefore, we have chosen MMP2, MMP9, Pyk2, and Cyclin D1 as tumor metastasis indicators to explore the mechanism of how PCDH9 and RAC1 act on melanoma." (PMID 36387162, 2022). "Furthermore, in melanoma cells, up-regulation of the thrombin receptor PAR-1 and the matrix metalloproteinase (MMP)-2, and down regulation of the c-KIT were found to be crucial for the metastatic progression of these cells." (PMID 34439864, 2021). "In vitro, activation of oxytocin receptor (OXTRs) promotes migration, invasion and angiogenesis of melanoma cells through the Arrestin2-dependent ERK-VEGF/MMP-2 pathway, but does not promote proliferation of melanoma cells." (PMID 34988010, 2021). "Moreover, metalloproteinases such as MMP1, MMP2, MMP13, and MMP14 secreted by CAFs facilitate melanoma invasion by participation in ECM digestion and, thus, the formation of a pathway used by cancer cells to move through the tissues." (PMID 33430277, 2021). "In melanoma cells, Wnt5a signaling enhances tumor angiogenesis, which involves a Ca2+-dependent release of exosomes containing pro-angiogenic proteins, VEGF and MMP2, whereas the promotion of exosomal secretion by Wnt5a can be inhibited by the calcium chelator Bapta." (PMID 34476217, 2021). "Altogether, these data indicate that, while our melanoma cells can produce MMP2, due to lack of signaling machinery, they cannot directly respond to it in an autocrine or paracrine manner." (PMID 34032639, 2021). "Overall, our results demonstrated that ASE inhibited the growth and migration of B16-F0 cells through downregulation of the VEGF, MMP-2, and MMP-9 genes expression, which indicates ASE could be applied for the prevention and treatment of melanoma." (PMID 35011253, 2021). "Thus, it is expected that ASE has an anticancer effect on melanoma and an inhibiting effect on melanoma invasion and metastasis through the reduction of the expressions of VEGF, MMP-2, and MMP-9, which are secreted during metastasis." (PMID 35011253, 2021). "Similarly, IL-33 affects the progression of malignant melanoma cells by binding to its receptor ST2 and inducing tumor cell proliferation, migration, and invasion through MMP-2, MMP-9, and ERK1/2 phosphorylation." (PMID 33466236, 2021). "β-Carotene treatment downregulates the expression of MMP-2 and MMP-9 by suppressing the nuclear translocation of p65, p50, c-Rel subunits of nuclear factor-kappa B, and other transcription factors, such as c-fos, a component of AP-1, in B16F-10 melanoma cells." (PMID 33809289, 2021). "In melanoma cell lines, an aggressiveness score based on TNF and MMP-2 has been described." (PMID 34204372, 2021).
melanoma (continued). "Upon stimulation with melanoma cell-conditioned media in vitro, fibroblasts increase gene expressions of matrix proteins, such as COL1A1 and COL1A2, as well as matrix remodelling proteins, such as MMP-2 and TIMP1." (PMID 34067929, 2021). "Additionally, in melanomas, MMP14 is expressed at the leading edge of the invasive front in melanoma and stromal cells in areas of strong MMP2 activation." (PMID 33924099, 2021). "Previously it was shown that in BRAF mutant melanoma cells, PLX treatment led to a decrease in the protein levels of N-cadherin and MMP2 among other EMT-related markers; however, when resistance to PLX developed, there was a significant increase in the expression of these proteins." (PMID 33810045, 2021). "Therefore, it is anticipated that the discovery of novel anticancer compounds that inhibit the expressions of MMP-2, and MMP-9 by VEGF will contribute toward overcoming skin cancer via the regulation of melanoma growth and metastasis." (PMID 35011253, 2021). "After the adhesion, melanoma cells both secrete serine-proteases which break the endothelial junctions of the blood–brain barrier (BBB) and disrupt its structure and release some other substance as the matrix metalloproteinase-2 (MMP-2) and heparinase." (PMID 32575838, 2020). "Linked by a network of overlapping functions in melanoma progression, melanoma cell adhesion molecule (MCAM), galectin-3 (Gal-3), chondroitin sulfate proteoglycan 4 (CSPG4), matrix metalloproteinase 2 (MMP-2), and paired box 3 (PAX-3) potentially act as biomarkers and targets in melanoma metastasis." (PMID 33490091, 2020). "Our results indicated that curcumol attenuated the expression of MMP2 and MMP9; therefore, we sought to determine whether curcumol was responsible for regulating epithelial-mesenchymal transition(EMT) in mouse melanoma B16 cells." (PMID 32194780, 2020). "In melanoma, upregulation of METTL3 expression was found to play a role in the invasion and migration of human melanoma cells by promoting the expression of matrix metallopeptidase 2 (MMP2)." (PMID 32398132, 2020). "Furthermore, our results indicated that curcumol decreased the expression of MMP2 and MMP9 in mouse melanoma B16 cells." (PMID 32194780, 2020). "Our in vivo studies showed that SB-3CT, an MMP2/9 inhibitor, could improve the efficacy of anti-PD-1 and anti-CTLA4 treatment in mouse models with melanoma and lung cancer, as well as metastatic melanoma in the lung." (PMID 32988398, 2020). "Our data show that treatment with naproxen-HBTA in mice with cutaneous melanoma was able to reduce the expression of MMP-2 and MMP-13 in tumor tissues confirming the efficacy of naproxen-HBTA in inhibiting the metastatic potential of B16F10 melanoma cells and the metastasis initiation in mice." (PMID 30800067, 2019). "CD133 may therefore play an essential role in invasion and metastasis via upregulation of MMP2/MMP9, leading to tumor progression, and represents an attractive target for intervention in melanoma." (PMID 31623313, 2019). "FAK is also a pivotal mediator of the aggressive melanoma phenotype, which is characterized by an increased expression of ERK1/2 to regulate the levels of urokinase activity or to enhance the expression of MMP-2 and MMP-14 activity, both signaling pathways contribute to VM formation." (PMID 31772665, 2019). "Recent studies based on mRNA and protein expression show that several MMPs, namely MMP-9, MMP-12 MMP-2, MMP-14, and MMP-19, play a role in melanoma aggressiveness and consequently may represent useful prognostic biomarkers." (PMID 30591049, 2018). "Inhibition of melanoma cell invasion by metformin is correlated with modulation of expression of proteins involved in epithelial-mesenchymal transition such as Slug, Snail, SPARC, fibronectin, and N-cadherin and with inhibition of MMP-2 and MMP-9 activation." (PMID 29245964, 2017).